POT1 (protection of telomeres 1)
Diseases named in the same sentence as POT1 in open-access papers (continued):
Sharing a sentence is not in itself a finding about the gene and the disease.
breast carcinoma (14 papers, 2007 to 2025). "Four POT1 mutations were identified significantly more frequently in breast cancer patients (n = 1067) than in healthy controls (n = 1110)." (PMID 32987645, 2020). "In breast-cancer cell lines, a significant reduction in POT1 mRNA level was associated with POT1 promotor methylation." (PMID 27486974, 2016). "We performed a case-control study to evaluate the role of three SNPs (TERT-07, TERT-54 and POT1-03) in telomere maintenance genes previously found to be significantly associated with breast cancer risk." (PMID 22970196, 2012). "We previously identified three genetic variants in telomere maintenance genes (TERT and POT1) that were significantly correlated with breast cancer risk in a large (1,067 cases, 1,110 controls) case-control study, the Long Island Breast Cancer Study Project." (PMID 22970196, 2012). "However, none of these polymorphisms have previously been linked to cancer risk, except the POT1 rs7794637 polymorphism, which is associated with breast cancer risk." (PMID 36834938, 2023). "For example, the POT1 variant rs35439397 has been associated with poor survival in breast cancer." (PMID 32987645, 2020). "POT1 was hyper-methylated and can be reactived by 5-aza-2′-deoxycytidine in breast cancer cell line." (PMID 28424414, 2017). "In a population-based study of 1995 breast cancer cases and 2296 controls from Poland, 24 SNPs representing common variation in POT1, TEP1, TERF1, TERF2 and TERT were genotyped." (PMID 17848914, 2007). "In our study, the identified truncating variant in TERF2IP occurred in a patient who also developed primary breast cancer (BUM4), hinting at a possible tumor predisposition syndrome associated with the TERF2IP gene, similar to the one described for the POT1 gene." (PMID 38892746, 2024). "In contrast, POT1 mRNA has been found downregulated in breast cancer." (PMID 32987645, 2020). "In our study, POT1 showed low level of methylation in breast cancer tissues." (PMID 28424414, 2017). "The TT genotyping of TERT-54 and AA genotyping of POT1-03 were inversely associated with breast cancer risk but the associations were not statistically significant (the ORs were 0.83 (95%CI: 0.44–1.57) and 0.48 (95%CI: 0.23–1.00), respectively)." (PMID 22970196, 2012). "Using data from a large population-based case-control study, we previously identified three genetic variants (TERT rs2736109, rs3816659 and POT1-03 rs33964002) in telomere maintenance genes associated with breast cancer risk, but no independent data has validated this finding." (PMID 22970196, 2012). "Within human breast cancer cell lines, expressions of TRF1, TIN2, and POT1 are upregulated by dexamethasone, suggesting activation of the glucocorticoid receptor, whereas TERT, TRF2, TRF1, TIN2, and POT1 are upregulated by TNF-α, suggesting activation of the NFκB transcription factor." (PMID 23342266, 2012).
cutaneous melanoma (12 papers, 2015 to 2025). A primary melanoma arising from atypical melanocytes in the skin. "A total of 49 POT1 variants purportedly associated with cancers other than cutaneous melanoma were identified in a recent comprehensive literature review." (PMID 40350252, 2025). "In 2014, POT1 was deemed as a novel high-penetrance susceptibility gene to cutaneous melanoma by two independent studies." (PMID 38254993, 2024). "Our aim here is to discuss the proposed cancer associations, other than cutaneous melanoma, related to the germline variants of POT1, reported mostly after 2014, in order to look at strengths, or weaknesses, of the data with a critical perspective." (PMID 38254993, 2024). "These individuals had reduced telomere-bounded POT1 levels, with longer and more fragile telomeres and one mutation carrier also developed cutaneous melanoma (CM)." (PMID 38839987, 2024). "Cutaneous melanoma is the most reported malignancy associated with POT1-TPDS." (PMID 40350252, 2025). "Functional and animal model studies thoroughly investigated the susceptibility variants found in cutaneous melanoma families, but after that, the number of cancers proposed as associated with the clinical spectrum of the POT1 predisposition tumor syndrome (POT1–TPD) increased." (PMID 38254993, 2024). "Since the identification of POT1 as a novel gene implied in rare hereditary forms of cutaneous melanoma, many studies proposing to add other cancers to the clinical spectrum of the so-called POT1–TPD have been published." (PMID 38254993, 2024). "Our analysis identified spitzoid morphology (≥25% of tumor) in 77% of cutaneous melanomas from POT1 carriers, consistent with a recent case series from our group where 60% of cutaneous melanomas from POT1 carriers exhibited this histology." (PMID 36876055, 2023).
sarcoma (12 papers, 2020 to 2025). A usually aggressive malignant neoplasm of the soft tissue or bone. "The available evidence was shared with a small working group of experts that included clinical geneticists, dermatologists, sarcoma specialists, haematologists and radiologists to cover all aspects of the cancers most commonly associated with POT1-TPDS." (PMID 40350252, 2025). "According to our findings, we consider that it would be important to discuss the inclusion of all types of sarcomas in the screening criteria for POT1 mutations." (PMID 38839987, 2024). "This is an important topic, since it is estimated that POT1 PV carriers have 6 times more risk of developing a sarcoma than POT1 wild type individuals." (PMID 38839987, 2024). "It was observed that heritable defects in POT1 increase the risk of cancers, including sarcomas, and study participants with POT1 mutations had significantly longer telomeres than age-matched controls." (PMID 37709802, 2023). "Nonetheless, our observations align with recent studies also reporting sarcoma (and cardiac angiosarcoma), CRC and PTC associated to POT1 PV." (PMID 38839987, 2024). "Further, another study reported higher prevalence of CM (13.2%) and sarcomas (3.5%) among POT1 PV carries." (PMID 38839987, 2024). "In agreement with previous studies, telomeric content was significantly higher in ATRX altered and POT1 altered sarcomas." (PMID 37709802, 2023). "Prevalence of RAD51B, GID4, and POT1 alterations varied widely across sarcoma subtypes and tended to mostly occur in diseases with high prevalence rates of alterations in the other telomere maintenance genes." (PMID 37709802, 2023). "Of all the genes associated with LFS/LFL or sarcoma that we have surveyed, we identified a novel p.P35L germline variant in POT1 (protection of telomeres 1)." (PMID 36387164, 2022). "Interestingly, the locus identified on chromosome 14 overlaps with the POT1 and POT1-AS1 genes, suggesting that genetic variants affecting genes related to telomeric maintenance play a role in sarcoma predisposition in dogs as well as in humans." (PMID 37505880, 2023). "Moreover, the data regarding the suppression of telomeric recombination events by mouse Pot1 suggest the hypothesis that some POT1 mutations may also facilitate activation of the ALT TMM, which is common in sarcomas." (PMID 32987645, 2020). "POT1-TPD was observed, but also a higher incidence of other cancers (other sarcomas, papillary thyroid cancer, early onset prostate cancer and leukaemia)." (PMID 38839987, 2024). "Across all sarcoma samples within our screening cohort, samples with alterations in either GID4, RAD51B, POT1, or ATRX had significantly higher telomeric content than WT samples." (PMID 37709802, 2023). "Furthermore, findings of a broader spectrum of diseases related to POT1-TPD should be considered for future guidelines, not only about the testing criteria for POT1 PV, but also to adapt the surveillance program to these other malignancies within the POT1-TPD (mainly sarcomas)." (PMID 38839987, 2024).
tumor predisposition syndrome (10 papers, 2021 to 2026). "Constitutional or germline pathogenic variants (GPVs) in protection of telomeres 1 (POT1) are associated with a variety of tumours resulting in the recognition of POT1-tumour predisposition syndrome (POT1-TPDS)." (PMID 40350252, 2025). "Germline mutations in this gene are causative of the POT1 tumor-predisposition syndrome (POT1-TPD), which is characterized by a broad spectrum of malignancies, such as BAP1-TPDS." (PMID 34356093, 2021). "POT1 tumour predisposition syndrome (POT1-TPD) has autosomal dominant inheritance and unknown penetrance." (PMID 38839987, 2024). "In individuals with germline POT1 variants, accumulation of distinct patterns of somatic alterations within tissue-specific progenitor cells likely underlies development of the vast array of cancers associated with the Li-Fraumeni-like POT1 tumor predisposition syndrome." (PMID 35456397, 2022). "Germline loss-of-function (LOF) variants in POT1 are associated with a rare oncological predisposition syndrome, known as POT1-tumor predisposition syndrome (POT1-TPD), with no more than 100 affected families currently reported." (PMID 39156708, 2024). "The spectrum of cancers associated with germline pathogenic POT1 variants (i.e., autosomal dominant POT1 tumor predisposition syndrome) should potentially be expanded to include SMZL, a disease often associated with the loss of chromosome 7q: the location of the POT1 genetic locus (7q31.33)." (PMID 35456397, 2022).
lung carcinoma (9 papers, 2015 to 2025). "Other types of cancer, such as colorectal cancer (CRC), thyroid cancer, other soft tissue sarcomas (STS), osteosarcomas, breast and lung cancers have also been associated with POT1-TPD." (PMID 38839987, 2024). "On the other hand, one can observe that individuals with the mutation also developed other types of cancers that have been described in association with mutation of POT1, but with less evidence, such as colon cancer, lung cancer, leukaemia and PTC." (PMID 38839987, 2024). "Only the rs116895242 near POT1 was evaluated as inversely associated with colorectal, ovarian, and lung cancers." (PMID 38254993, 2024). "Recently, genome-wide association studies (GWAS) have pointed out an association between POT1 variants and lung cancer." (PMID 39156708, 2024). "Furthermore, given that major genetic factors for lung cancer predisposition are still to be identified, our study provides the first reported clinical evidence supporting previous genome-wide association studies that indicate a potential association between POT1 variants and lung cancer." (PMID 39156708, 2024). "This case report highlights the clinical relevance of POT1 alterations, particularly their potential involvement in lung cancer." (PMID 39156708, 2024). "A study with more than 30,000 lung cancer patients showed that POT1 mutations play a role in lung cancer predisposition, however, without further data it is not possible to draw a clear conclusion on the association of POT1 PV and lung cancer." (PMID 38839987, 2024). "We think that the presence of this variant in non-smokers with lung cancer is interesting and further supports our finding that POT1 alteration is the driving event in our patients." (PMID 36387164, 2022). "Two previous studies in breast and lung cancer in Polish and Chinese populations did not observe any association between POT1 polymorphism and disease risk." (PMID 26143636, 2015). "Expression levels of shelterin complex genes were previously studied in lung cancer, but only TRF1, TRF2, POT1, and RAP1 mRNA were measured in early NSCLC, and no consistent pattern of expression was identified." (PMID 36612286, 2022).
familial cancer (8 papers, 2015 to 2025). "By extension, we argue that there is no need to invoke genome instability as a cancer-promoting aspect of the POT1 mutations in familial cancer." (PMID 33258446, 2020). "Germline mutations of POT1 have also been identified in other familial cancers." (PMID 32987645, 2020). "The possible involvement of genes like BRCA1, BRCA2, CHEK2, and POT1, which are known to play a role in other hereditary cancers, could lead to new knowledge of UM, especially in family cases." (PMID 39926282, 2025).
colorectal cancer (7 papers, 2018 to 2024). A primary or metastatic malignant neoplasm that affects the colon or rectum. "An analysis of thousands of familial colorectal cancer cases alongside healthy controls identified three POT1 germline mutations (p.Asp617GlufsTer9, p.Arg363Ter and p.Asn75LysfsTer16)." (PMID 32987645, 2020). "POT1 was designated as one of three novel candidate colorectal cancer susceptibility genes, alongside MRE11 and POLE2." (PMID 32987645, 2020). "In colorectal cancer, there is a significant association between POT1 expression and clinical features such as cancer stage, site of occurrence and lymph node metastasis." (PMID 32987645, 2020). "For example, POT1 mRNA expression has been found upregulated in colorectal cancer, renal cell cancer, hepatocellular carcinoma, multiple myeloma and mantle cell lymphoma." (PMID 32987645, 2020).
gastric cancer (6 papers, 2009 to 2023). A primary or metastatic malignant neoplasm involving the stomach. "POT1 mRNA concentrations have been significantly linked with telomere length in colon and gastric cancer cells." (PMID 34947936, 2021). "POT1 protein levels are associated with telomere length in gastric cancer." (PMID 24260532, 2013). "Furthermore, in gastric cancer, POT1 expression has been associated with cancer stage." (PMID 32987645, 2020). "In gastric cancer, POT1 mRNA expression detected by quantitative reverse transcriptase polymerase chain reaction (qRT-PCR) was significantly upregulated in tumors when compared with para-cancer tissues." (PMID 32987645, 2020). "In a further independent study, POT1 protein expression detected by Western blot and immunohistochemistry was reduced in both gastric cancer cell lines and gastric tumors when compared with control samples." (PMID 32987645, 2020). "The amount of POT1 mRNA in the case of stomach cancer often decreases in the early stages and increases at more advanced stages." (PMID 22649586, 2009). "Apart from this, the inhibition of POT1 in the stomach cancer cell lines by the anti-sense oligonucleotides, similarly to the inhibition of telomerase activity, also leads to telomeres shortening." (PMID 22649586, 2009).
Hodgkins lymphoma (6 papers, 2020 to 2025). A heterogeneous group of malignant lymphoid neoplasms of B-cell origin characterized histologically by the presence of Hodgkin and Reed-Sternberg (HRS) cells in the vast majority of cases.
osteosarcoma (6 papers, 2017 to 2024). A usually aggressive malignant bone-forming mesenchymal neoplasm, predominantly affecting adolescents and young adults. "In those with European ancestry, POT1 germline mutation frequency was statistically significantly enriched in those with disease (0.5%, n = 4/732), indicating a potential association between POT1 germline variants and risk of developing osteosarcoma." (PMID 32987645, 2020). "We found that GFP-tagged POT1 is rapidly recruited to DNA damage sites in a human bone osteosarcoma epithelia cell line U2OS, while GFP itself is not recruited to DNA lesions." (PMID 29227966, 2017).
B-cell lymphoma (5 papers, 2015 to 2025). "Studies have shown that mutations in POT1 are often found in patients with B-cell lymphoma, and that POT1 gene mutation can lead to the occurrence of various tumors, such as lymphomas." (PMID 36059700, 2022). "POT1, the most significantly somatically mutated gene in the Gr and Cs B-cell lymphomas combined, encodes a protein important for telomere maintenance, and mutations in this gene predispose to several types of cancer in human." (PMID 26377837, 2015). "The top most significantly mutated genes in B-cell lymphomas are POT1, FBXW7, and TRAF3." (PMID 26377837, 2015). "Strong similarities were evident between B-cell lymphomas from golden retrievers and cocker spaniels, with recurrent mutations in TRAF3-MAP3K14 (28% of all cases), FBXW7 (25%), and POT1 (17%)." (PMID 26377837, 2015). "In addition to these findings, multiple somatic point mutations were identified in canine B-cell lymphoma including TRAF3, POT1, LMNB1 and MVB12A19–21." (PMID 35332215, 2022). "One study assessed the prevalence of TRAF3 and POT1 mutations in a cohort of canine B-cell lymphomas (cBCL), but their clinical significance was not investigated." (PMID 36016811, 2022).
lymphoma (5 papers, 2022 to 2025). A malignant (clonal) proliferation of B- lymphocytes or T- lymphocytes which involves the lymph nodes, bone marrow and/or extranodal sites. "In contrast to TRAF3, the POT1 VAF of 51% was discordant with the frequency of lymphoma cells and suggestive of a potential heterozygous germline variant." (PMID 35456397, 2022). "Thus, a significant mechanism of lymphoma development in dogs caused by TRAF3 and POT1 mutations pivotally requires further study." (PMID 39176397, 2024). "During the clinical workup of his low-grade lymphoma, targeted next-generation sequencing (NGS) identified POT1 p.I49Mfs*7 (NM_015450:c." (PMID 35456397, 2022).
myeloproliferative neoplasm (5 papers, 2022 to 2025). A clonal hematopoietic stem cell disorder, characterized by proliferation in the bone marrow of one or more of the myeloid (i.e., granulocytic, erythroid, megakaryocytic, and mast cell) lineages. "A recent study on a case series of 3323 patients with different diagnoses of myeloproliferative neoplasm identified several somatic, germline, and putative germline POT1 variants." (PMID 38254993, 2024). "Recent studies implicate germline POT1 alterations in predisposition to a wide variety of hematologic malignancies, including myeloproliferative neoplasms and pediatric acute myeloid leukemia." (PMID 35456397, 2022). "Moreover, the cases of leukaemia described in these POT1 carrier families are in accordance with more recent data about the link between POT1 PV and the higher risk of B/T-cell lymphoproliferative and myeloproliferative diseases." (PMID 38839987, 2024). "Moreover, POT1 variant carriers seem to have a higher risk of B-cell and T-cell lymphoproliferative and myeloproliferative disease." (PMID 38839987, 2024).